IL13RA2 (interleukin 13 receptor subunit alpha 2)
Diseases named in the same sentence as IL13RA2 in open-access papers (continued):
Sharing a sentence is not in itself a finding about the gene and the disease.
tumor (continued). "Another target of CAR-T cell treatment for GBM patients is IL-13Rα2, which presents in more than 75% of GBM tumors associated with tumor invasiveness and poor prognosis." (PMID 33767690, 2020). "Eradication of cells expressing IL13RA2 by CAR T cells can therefore also increase anti-tumor immunity." (PMID 32983080, 2020). "TCGA database analysis revealed that the expression of IL13RA2 was higher in normal hepatic tissue compared with its expression in tumor." (PMID 31823484, 2020). "We then stratified the data based on IHC immunostaining for IL-13Rα2 positivity, which revealed that 56 (36%) samples demonstrated IL-13Rα2 positive tumor cells that had invaded PL and were of moderate to poor pathological grade." (PMID 32443847, 2020). "Similar to the antigen targeted by CAR-T cells, the vaccine target needs to cover tumor-specific antigens such as EGFRvIII and IL-13Rα2." (PMID 33511267, 2020). "After treatment, the overall expression of IL13-Rα2 in some patients decreased, while the tumor necrotic volume increased at the site of IL13-zetakine(+) T-cell administration." (PMID 33224149, 2020). "IHC results show that the extent of immunostaining for IL-13Rα2 is significantly higher as the grade advances from well differentiated to moderately to poorly differentiated PDAC tumor samples." (PMID 32443847, 2020). "Extensive studies have suggested that monocytes/TAMs exert a pro-tumorigenic effect by the secretion of chitinase-3-like 1 (CHI3L1, YKL-40), interleukin-13 receptorα2 (IL-13Rα2) and then facilitating tumor cell invasion and migration." (PMID 30962764, 2019). "The tumor antigens that have been most investigated for CAR targets in GBM to date are IL-13Ra2, EGFRvIII, and Her2." (PMID 30790064, 2019). "IL13Rα2 staining pattern varied among tumour tissue samples examined with IL13Rα2 staining observed in >90% tumour cells in a tumour tissue sample obtained from one patient." (PMID 30718742, 2019). "For one patient, tumor material before and after therapy was available, which indicated reduced IL-13Rα2 expression in the tumor after treatment." (PMID 31798595, 2019). "The level of amphiregulin expression was increased in the tumours originated from the SK-IL13Rα2 cells as compared with those from the SK-MEL-28 cells, suggesting a positive correlation between IL13Rα2 and amphiregulin expressions." (PMID 30718742, 2019). "To confirm the upregulation of AP-1 transcription factors in IL-13Rα2 positive GBM tumor cell lines at molecular level, we performed RT-qPCR analysis to quantitate mRNA expression of all five AP-1 transcription factors in IL-13 treated GBM cell lines." (PMID 30572904, 2018). "Preliminary results from a Phase I trial of a first-generation CAR-T cells targeting the glioblastoma tumor antigen IL13Rα2 reported safe intracranial delivery of the CAR-T cells with one particular patient exhibiting a 79% regression of recurrent tumour mass." (PMID 29854316, 2018). "IL13Rα2 expression is found predominantly only in the tumor induced sciatic nerve, whereas very weak expression is found in the normal sciatic nerves as evident from immunoblots with the tissue lysates and IHC with the paraffin embedded tissue sections." (PMID 29304038, 2018). "Specifically, we observed that monocytes from mCRPC promoted tumor invasiveness via an IL‐13Rα2‐dependent mechanism." (PMID 30094958, 2018). "Ephrin type A receptor 2 (EphA2), IL-13Ra2, and HER2 represent promising tumor associated antigens that have been targeted both pre-clinically and clinically using CAR T-cell therapy in the setting of GBM." (PMID 30740109, 2018). "It has been reported that IL-13Rα2, acting as a decoy receptor, has an intimate relationship with the progression of a tumor and can undergo internalization after binding to ligands." (PMID 30723412, 2018). "It is also shown that IL-13Rα2 can protect tumor cells from apoptosis thereby contributing to tumor growth." (PMID 29168083, 2018).
tumor (continued). "Previous work by another group has verified the glycosylation of IL13Rα2 to be a significant event in tumor progression." (PMID 29304038, 2018). "The interleukin 13 receptor α2 (IL-13Rα2) is a subtype of the interleukin-13 receptor family, which is over-expressed on tumor cells." (PMID 30723412, 2018). "In one such phase I human clinical trial, following surgical tumor debulking, IL13Rα2-targeted CARTs were infused into the resection cavity via a Rickham catheter." (PMID 30386740, 2018). "IL13Rα2 is established as an oncogenic receptor and plays a significant role in tumor cell migration, invasion and anti-apoptotic activity." (PMID 29304038, 2018). "The therapeutic effect seen in the tumor bearing mice is amplified upon targeting the liposomes to IL13Rα2." (PMID 29304038, 2018). "To demonstrate tumor specific delivery of Pep1L, a novel peptide discovered to target IL13RA2, we radiolabeled it with positron emitting Cu-64 and demonstrated its ability in vitro and in vivo to target IL13RA2-expressing human GBMs." (PMID 28562337, 2017). "In vivo FMT imaging data provided biodistribution profiles for the IL13Rα2 Ab-F conjugates in the whole-body, the liver, the tumor and the heart." (PMID 28915667, 2017). "As expected, due to the tumor-targeting properties of the IL13Rα2 Ab, the images show a continuous increase in Ab-AF680 signal until 48 h post-injection." (PMID 28915667, 2017). "We analyzed IL-13Rα2 mRNA expression from primary tumor patient samples obtained from the Repository for the Molecular Brain Neoplasia Data (REMBRANDT) of the National Cancer Institute." (PMID 29203859, 2017). "We and others have demonstrated that IL13RA2 is an attractive tumor-restricted biomarker that is highly over-expressed on the vast majority of GBMs and is internalized after ligand engagement." (PMID 28562337, 2017). "The levels of IL-13Rα2 expression correlates with tumor grades of astrocytomas, and is a prognostic indicator of poor patient survival." (PMID 29203859, 2017). "Knowing each tumor's IL13RA2 expression profile can help personalize IL13RA2-targeted therapies to patients that have tumors that express significant amounts of IL13RA2." (PMID 28881623, 2017). "Targeted knockdown of IL-13Rα2 in primary wtEGFR-positive GBM patient tumor, as validated by western blot analysis, also did not affect cell proliferation nor cell migration." (PMID 29203859, 2017). "Kaplan-Meier analysis was also applied to compare overall survival according to IL-13Rα2 expression in different TNM stage in tumor tissues." (PMID 27351230, 2016). "Recent years, IL-13Rα2, a so-called decoy receptor, has been shown to be highly expressed in many tumor types, such as head and neck, glioblastoma and lung, and was also shown to promote invasion and metastasis of colorectal, ovarian and pancreatic cancers." (PMID 27533463, 2016). "To further explore the prognostic significance of IL-13Rα2 expression according to different clinicopathological factors, we performed Kaplan-Meier analysis in patients with different depth of tumor invasion." (PMID 27351230, 2016). "The cytotoxic role of IL-13PE to IL-13Rα2 expressed tumor was confirmed by plasmid-mediated gene transfer and knock-down experiments in vitro and in vivo." (PMID 27351230, 2016). "On the other hand, Ki67 staining revealed modest reduction in mitotic activity of IL13Rα2-depleted tumors consistent with the corresponding reduction in tumor weight." (PMID 26208975, 2015). "In our model, overexpression of IL13RA2 inhibited tumor apoptosis induced by sunitinib and silencing of IL13RA2 promoted tumor apoptosis induced by sunitinib." (PMID 26114873, 2015). "The interleukin-13 receptor α2 (IL-13Rα2), one of the subunits of the interleukin-13 receptor, is a tumor-specific receptor which is overexpressed in GBM." (PMID 26567528, 2015). "And patients with high IL13RA2 expression in immunohistochemistry in primary ccRCC tumor tends to have sunitinib-resistant metastatic site." (PMID 26114873, 2015).
tumor (continued). "Previous studies have shown that IL-13-PE can bind to IL-13Rα2 positive tumor cells and is highly cytotoxic to these cells in both in vitro and in vivo models of multiple malignancies 16,18,19." (PMID 25767039, 2015). "Consistent with the results obtained from the in vitro assays, silencing of IL13Rα2 inhibited xenograft tumor growth (P = 0.01)." (PMID 26418721, 2015). "Among these receptors, IL-13Rα2 has attracted increasing interest for its potential role in tumor-specific therapeutics." (PMID 26567528, 2015). "IL13Rα2 positive expression also correlated with poor tumor differentiation (P = 0.02), nodal status (P = 0.01) and TNM stage (P = 0.001)." (PMID 26418721, 2015). "We found that there was a delay in the tumor growth of IL13Rα2-depleted MIV-Luc cells compared with controls and that this was attributed predominantly to a significant, albeit modest, reduction during days 12–16 post-injection." (PMID 26208975, 2015). "The consistency of the obtained results seems to support the use of the selected AAAs, in particular IL13Rα2 and Fra-1, as tools facilitating the establishment of tumour-derived cultures." (PMID 25788865, 2014). "IL13RA2 overexpressing tumor cells produced high levels of IL-8 which has been shown to reduce tumorigenicity in several tumor models." (PMID 25481245, 2014). "The monoclonal antibody can be either delivered directly as antibody fragments with stabilizing agents, as it has been shown that targeting molecules, both antibodies as well as IL13Rα2-targeted peptides has properties of homing to the tumor sites." (PMID 25247196, 2014). "In preclinical tests, CAR T cells designed to target IL13Rα2 produced copious amounts of immunostimulatory cytokines in presence of IL13Rα2-expressing GBM tumor cell lines as well as patient tumor cells indicating the high specificity." (PMID 25247196, 2014). "It has been established through early successful preclinical studies on first-generation CAR T cells that the IL13.E13Y zetakine (IL13 zetakine) T cells induced secretion of IFNγ, TNFα, and GM-CSF only in the presence of IL13Rα2-expressing tumor cells." (PMID 25247196, 2014). "The IL13Rα2 immunoreactivity was found in all tested tumour specimens, while Fra-1 antigen was detected in four tested samples." (PMID 25788865, 2014). "Strong membrane and cytoplasmic reactivity for IL13Rα2 was found in three tumour sections, and weak cytoplasmic staining was observed in two other cases." (PMID 25788865, 2014). "The analyses verified subsequently at the protein level showed the IL13Rα2 immunoreactivity in all tumour specimens, and Fra-1 antigen in four of the five examined samples." (PMID 25788865, 2014). "CARs can be designed to express either antibody to target peptide antigens on the tumor surface or ligands to target tumor-specific receptors (in this case IL13 muteins as ligands for IL13Rα2 on GBMs)." (PMID 25247196, 2014). "T cells engineered to target IL13Rα2 have also shown tumor recognition and anti-tumor effector function." (PMID 24273748, 2013). "No IPA-defined pathways for proneural signature genes were shared with IL13Rα2 (or were immune related), consistent with the antiphase correlation with IL13Rα2 expression shown by signature genes of the mesenchymal and proneural tumor sublasses." (PMID 24204956, 2013). "In this more physiological tumor segmentation, IL13Rα2 expression was well correlated with both the mesenchymal and proliferative signature genes, consistent with our observations linking IL13Rα2 expression to poor patient prognosis." (PMID 24204956, 2013). "It recognized IL-13RA2 in cell and tumor lysates using western blot and resulted in robust immunohistochemical staining in archival paraffin embedded specimens." (PMID 24147065, 2013). "We looked at the tumor tissues from treated Tgfbr1/Pten 2cKO mice to see if the expression of IL-13Rα2 was decreased." (PMID 23421960, 2013).
tumor (continued). "We therefore examined patient survival in the 870 WHO Grade IV tumor cohort previously evaluated for the IL13Rα2 survival analysis above." (PMID 24204956, 2013). "The cultured primary tumor cells with upregulated IL-13Rα2 were sensitive to the addition of IL-13-PE in a dose-dependent manner." (PMID 23421960, 2013). "We discovered that the tumors derived from these Tgfbr1/Pten double conditional knockout (2cKO) mice over-expressed IL-13Rα2, a high affinity receptor for IL-13 that can function as a tumor antigen." (PMID 23421960, 2013). "IL-13Rα2 is also an ideal target for cytotoxin-based therapy since it is a unique tumor target displaying a high affinity for IL-13 and undergoes endocytosis upon binding." (PMID 23421960, 2013). "IL-13RA2 belongs to a group of cancer/testis like tumor antigens and is one of the downstream gene targets following activation of both wild type EGFR and mutant EGFRvIII." (PMID 24147065, 2013). "In this limited tumor dataset, IL13Rα2 is also highly over-expressed in the proliferative subtype of Phillips, and the neural subtype of Verhaak." (PMID 24204956, 2013). "IL-13-PE is highly cytotoxic to tumor cells in vitro and in vivo that express high levels of IL-13Rα2." (PMID 21477288, 2011). "This tumor growth pattern was the same as the IL-13Rα2 DNA vaccine alone, indicating that the boost with ECDα2 generated IL-13Rα2 specific immune response." (PMID 21067607, 2010). "In MCA304 tumor model, ECDα2 boost vaccine showed protection from tumor growth compared to IL-13Rα2 DNA vaccine alone." (PMID 21067607, 2010). "We have previously reported that vaccination of human IL-13Rα2 cDNA alone in D5α2 model generated antibodies, which were modestly cytotoxic to D5α2 tumor cells in vitro." (PMID 21067607, 2010). "To enhance the effectiveness of DNA vaccine, we used extracellular domain of IL-13Rα2 (ECDα2) as a protein-boost against murine tumor models." (PMID 21067607, 2010). "Studies using tumor cells have shown that the expression of IL13RA2 up-regulates that of STAT3, which ultimately compromises the IL-13 signal." (PMID 21179488, 2010). "Mice receiving IL-13Rα2 DNA vaccine boosted with ECDα2 protein were superior in exhibiting inhibition of tumor growth, compared to mice receiving DNA vaccine alone, in both prophylactic and therapeutic vaccine settings." (PMID 21067607, 2010). "IL13-PE cytotoxicity toward an IL-13Rα2-expressing tumor cell line in the presence of mouse sera from various groups of treated micea." (PMID 20090941, 2010). "Mice with MCA304 tumors showed inhibition of tumor growth when vaccinated with IL-13Rα2 DNA vaccine alone." (PMID 21067607, 2010). "On day 30, the tumor volume of MCA304 tumors in mice receiving the ECDα2 boost protein (252 mm3) was significantly smaller than that of mice receiving the IL-13Rα2 DNA vaccine alone (1334 mm3) (P < 0.01)." (PMID 21067607, 2010). "The tumor volume in ECDα2 boosted mice at day 27 was significantly smaller (177 mm3) than that of the IL-13Rα2 DNA vaccine alone mice (775 mm3, P < 0.01)." (PMID 21067607, 2010). "have evaluated different amine-reactive NIR fluorophores, such as Alexa Fluor 647®, Alexa Fluor 680®, and Alexa Fluor 750®, in preclinical studies of the biodistribution and tumor binding of an interleukin-13 receptor subunit alpha-2 antibody (IL13Rα2-Ab) in mice and cell lines; Duygu and Cols." (PMID 41601978, 2026). "For example, a CAR T-cell that is AND-gated may be designed to activate only when it comes into contact with EGFRvIII and IL-13Rα2 on the same tumor cell." (PMID 40585996, 2025). "Overall, our work suggests that in metastatic TNBC, inhibition of IL13RA2 may be deleterious to patients, though patients with IL13RA2-low tumor may benefit from AKT inhibitors." (PMID 40663259, 2025).
tumor (continued). "The mechanism of action for ICT-107 involves pulsing autologous dendritic cells with peptide epitopes from six antigens—MAGE-1, HER-2, AIM-2, TRP-2, gp100, and IL13Ra2—targeting both tumor cells and cancer stem cells to reduce tumor heterogeneity and limit tumor escape." (PMID 40143152, 2025). "Notably, the efficacy of checkpoint blockade appears to depend on the specific CAR T-cell construct employed, as CAR T cells targeting EGFRvIII and IL13Rα2 induce distinct checkpoint expression profiles within the tumor microenvironment." (PMID 40867165, 2025). "The recent developments enabling the use of CAR-T cells targeting specific antigens, such as IL13Rα2, in conjunction with tumor lysates can enhance the effectiveness of the immune response by promoting direct interactions between modified T cells and tumor cells." (PMID 41374974, 2025). "Given that EGFRvIII and IL-13Rα2 are co-expressed in the same tumor cells, the intracellular tandem specificity between these two molecules may confer a growth advantage to the tumor, making them an ideal combination for simultaneous targeting." (PMID 40303292, 2025). "Notably, while IL-13Rα1 is ubiquitously expressed in healthy tissues, IL-13Rα2 exhibits tumor-specific overexpression with minimal distribution in normal organs, positioning it as a high-value target for chimeric antigen receptor (CAR) T-cell therapy in PDAC." (PMID 40948749, 2025). "A bifunctional CAR that targets both EGFRvIII and IL-13Rα2 may, for instance, also release IL-12 to attract and activate more immune cells in the tumor microenvironment." (PMID 40585996, 2025). "Studies utilizing single-cell RNA sequencing and spatial transcriptomics have shown that under the selective pressure of immunotherapies such as CAR T cells or monoclonal antibodies targeting EGFRvIII and IL13Rα2, tumor subclones can downregulate these target antigens." (PMID 41583467, 2025). "In addition to utilizing IL13RA2 as a tumor-specific target, there is interest in blocking IL13RA2 signaling itself." (PMID 40663259, 2025). "The results of the study showed that overexpression of IL-13Rα2 alone causes only tumor invasion, without further proliferation." (PMID 38339374, 2024). "The extent of the improvement provided by checkpoint inhibitors appears to be contingent upon the specific CAR-T-cell utilized, as CAR-T cells directed against EGFRvIII and IL13Rα2 each promoted distinct immune checkpoint environments within their respective tumor settings." (PMID 38727262, 2024). "More and more studies have found that IL13RA2 expression is related with tumor progression." (PMID 39220137, 2024). "Widespread IL13Ra2 expression in BSG, particularly elevated in the H3F3A mutant group, was strongly correlated with H3F3A mutations, increased proliferation, and heightened tumor stemness." (PMID 38201655, 2024). "Despite transient regression of the tumor, along with corresponding increases in cytokines and immune cell levels in the cerebrospinal fluid, patients died, most likely due to downregulation of the target antigen IL13Rα2." (PMID 38473776, 2024). "Early-phase clinical data suggest that IL13Rα2-targeted CAR-T cell therapy may induce tumor regression and improve survival outcomes in a subset of patients with recurrent GBM." (PMID 39000281, 2024). "Interestingly, xenografts grew faster from tumour cells expressing more IL‐13Rα2 receptor sites such as U251 compared to those from lower number of IL‐13Rα2 expressing tumour cells such as U87MG tumour cells." (PMID 38685487, 2024). "Thus, immune targeting of IL‐13Rα2 as a tumour antigen provides a unique opportunity for a targeted immunotherapy for IL‐13Rα2 positive solid tumour." (PMID 38685487, 2024). "The patient received CAR-T cells directed against IL13Rα2, which led to a regression of the tumor." (PMID 39531784, 2024).